Y_RNA (Y RNA )
Gene: Miscellaneous RNA gene on chromosome 9 (114,615,455 to 114,615,568, reverse strand). Ensembl gene ENSG00000201749.
Homologues: Orthologues: chimpanzee Y_RNA (96% identical). Paralogues in human: RNY1 (86% identical), Y_RNA (86% identical), Y_RNA (85% identical), Y_RNA (84% identical), RNY1P11 (83% identical), Y_RNA (83% identical), RNY1P7 (82% identical), Y_RNA (82% identical), Y_RNA (81% identical), Y_RNA (80% identical), RNY1P12 (79% identical), RNY1P8 (79% identical), and 96 more.